JUND (JunD proto-oncogene, AP-1 transcription factor subunit)
Diseases named in the same sentence as JUND in open-access papers (continued):
Sharing a sentence is not in itself a finding about the gene and the disease.
cancer (51 papers, 2001 to 2026). A tumor composed of atypical neoplastic, often pleomorphic cells that invade other tissues. "All these findings combined indicate that both JUNB and JUND are implicated in several cellular processes associated with cancer, either as suppressors of its progression or as promoters." (PMID 41020863, 2025). "JUNB and JUND are two transcriptional factors (TFs) of increased interest in cancer, regulating the expression of genes associated with survival, proliferation, differentiation, migration, invasion, angiogenesis, adhesion, apoptosis, and cell cycle regulation." (PMID 41020863, 2025). "JunD over expression has been associated with several cancer types." (PMID 34316331, 2021). "The FOS protein interacts with a panel of other proteins (c-Jun, junB, junD, FosB, Fra-1 and Fra-2) and forms the heterodimeric complex of Activator Protein-1 (AP-1) transcription factors which mediates multiple functions of cancer cells and is implicated as a driver of tumorigenesis." (PMID 30559931, 2018). "Furthermore, we found that the onco-suppressive effects of Salin may partially mediate MMP9 expression via the JNK/JunD pathway, causing the suppression of cancer cell invasion and migration." (PMID 25522777, 2015). "JUND, another AP-1 transcription factor, has been shown to contribute to the malignancy of several cancers by regulating cell proliferation and apoptosis." (PMID 41323280, 2025). "This role for JUND as a promoter of migration and invasion has also been reported in other cancer types, thus highlighting its targeting as a potential antimetastatic approach." (PMID 41020863, 2025). "Several studies credit JUNB or JUND with contradictory roles, even in the same cancer model or disease subtype, and this is a direct result of their participating in AP-1 complexes with a pro-transcription or suppressive activity." (PMID 41020863, 2025). "FOSL1 and JUND are also significant as they have been shown to drive metastasis and invasion in various cancers." (PMID 41323280, 2025). "The volcano plot of DEGs between 11 wart and 7 cancer samples of patients with EV shows differential expression of cancer-associated genes, such as FOS, JUND, PCNA, CHEK1, and CDKN2A." (PMID 36602881, 2023). "In contrast, CX3CR1low TEFF highly expressed activator protein-1 (AP-1) family genes (FOS, FOSB, JUNB, JUN and JUND), which were cancer-related transcription factors." (PMID 37080999, 2023). "This is also consistent with the motif enrichment result that enriched TFs in the PRC2−-CGI class were strongly overlapped between different cancer types, and were associated with cell-cycle TFs, such as SP1, JUND, NFY, E2F4, and E2F1." (PMID 33931649, 2021). "JunD activation therefore enhanced the metastatic potential of cancer cells, since in the presence of JunD, arecoline sequestered ZO-1 from the membrane to the cytosolic fraction of the cells, thereby lifting the cell barrier." (PMID 34316331, 2021). "These factors are known to interact with both the JunD and β-catenin pathways and to play relevant roles in cancer progression." (PMID 34446068, 2021). "Primary oral SCC (OSCC) showed heterodimers of c-Fos/JunD, which constituted the most prevalent AP-1 complex in cancer lesions." (PMID 33344262, 2020). "The network shows that JUND serves as a hub in K562 and plays important roles in cancer by interacting with other TFs." (PMID 30598100, 2018). "Several studies have reported that functional loss or downregulation of AP-1, or post-transcriptional control of JunD by miRNA can effectively suppress the proliferation of cancer cells." (PMID 29661228, 2018). "Taken together, we have shown that the FOXA1/JUND /FOSL2-TXNDC9-MYC regulatory network promoted cancer progression of HCC." (PMID 30382079, 2018). "JUND/JUNB is part of the AP-1 TF complex, which has been implicated in a broad array of cancer-relevant phenotypes including proliferation and apoptosis." (PMID 29312534, 2017).
cancer (continued). "Western blotting was performed to study the expression pattern of AP-1 family proteins (c-Jun, JunD, JunB, c-Fos, FosB, Fra-1 and Fra-2) in all spectrum of tongue tissue biopsies from normal, precancer to cancer including TSCC cell lines." (PMID 26581505, 2015). "JUND, part of the AP-1 transcription factor family, oversees vital cellular functions like growth and differentiation and plays a role in regulating immune responses, inflammation, and cancer development." (PMID 38739758, 2024). "Given that the upregulation of the tumor suppressor heat shock protein 4 (HLJ1) mediated by JunD, an activator protein (AP‐1) component, can inhibit the migration and invasion of cancer cells via E‐cadherin, we examined the impact of TP73‐AS1 on the expression of these proteins." (PMID 35871358, 2023). "On the other hand, JUND, a member of the AP-1 family that is related to MYC signaling pathway, regulates cell cycle and proliferation and its overexpression is linked to many types of cancers (PCA i.e.,)." (PMID 35741808, 2022). "Interestingly, JunD/JunD homodimer often observed in precancerous oral lesions appears to prevent progression to cancer, but its participation with c-Fos induced lesions to progress to invasive cancer." (PMID 26581505, 2015). "JUND protein expression was increased in cancer cells compared to normal urothelial cells." (PMID 16265353, 2005). "For example, DNA methylation by JunD may be related to cancer cell apoptosis." (PMID 30279327, 2018). "Several cancer-related TFs such as JUNB, JUND, Forkhead box protein M1 (FOXM1), and ETS1 were part of the TF–mRNA regulatory network." (PMID 36232337, 2022). "Others were either showed to have a cancer-specific co-transcription pattern, such as miR-34/BTG4, or had independent transcription, such as miR-3188/JUND." (PMID 34572448, 2021). "Other members of the Jun family, such as JUNB and JUND, were found to have opposing functions to that of c-JUN, and in most cancers are observed to exhibit decreased expression." (PMID 21711548, 2011). "Notably, D_FB1 displays elevated levels of other cancer‐ and inflammation‐related genes—such as DNAJB1, ZFP36, JUND, TNFAIP3 and IL6—further underscoring a microenvironment characterised by heightened cellular stress and chronic inflammation." (PMID 41055332, 2026). "The expression of JUND and RPS6KA2 is tightly and positively correlated in various cancer types." (PMID 31937753, 2020). "It included a number of genes with obvious cancer relevance including CD44, catenin b1 (CTNNB1), vimentin (VIM), cathepsins B and S (CTSB, CTSS), MMP9, XIAP, JunD, numerous proto-oncogenes (REL, YES, SET, FGR, CRK), and HSP90AA1 (which is a chaperone which stabilizes MIF as a client)." (PMID 28957348, 2017). "Furthermore, we analyzed our original chromatin accessibility data,and found that the DNA binding motifs of ELF1, JUND, and SPI1, which arepotential transcription factors of PARP10, NIPAL1 and ZYG11B in CRC tissues, arespecifically open in cancer tissues compared with adjacent tissues." (PMID 41020586, 2025). "Therefore, in cancer cells exposed to arecoline, JunD is activated not by phosphorylation alone but by interaction with NEAT1 to suppress the expression of ZO-1 and destabilize structural integrity of TJs." (PMID 34316331, 2021). "On the other hand, JUN, JUND, and FOSL1, another set of potential targets of HSF1 upregulated after heat shock, were expressed at higher levels (or not significantly changed) in all analyzed HSF1high cancers." (PMID 36010586, 2022).
infection (3 papers, 2022 to 2025). The state of being infected such as from the introduction of a foreign agent such as serum, vaccine, antigenic substance or organism. "Under Ad-vaspin infection, we observed increases in the levels of c-Fos and c-Jun but no changes in Fosl1, Fosl2, FosB, JunB or JunD." (PMID 40025171, 2025). "Interestingly, the expression of PRRs, MAPK signaling pathway genes (MyD88, AP-1, c-fos, Jun, JunD, MAX, and c-Myc), cytokines, chemokines, IFNs, and IFN-stimulated genes were increased after infection in resistant chickens." (PMID 34991196, 2022).
adenocarcinoma (1 paper, 2021). A common cancer characterized by the presence of malignant glandular cells. "JunD protein, on the other hand, was abundant in normal mucosa and only showed a slight increase in adenocarcinomas." (PMID 34836311, 2021).
cardiovascular disease (1 paper, 2022). "We constructed an mRNA–miRNA–lincRNA ceRNA interaction network centered on miR-22-3p and used the starBase v2.0 and miRWalk databases to predict eight related transcription factors associated with cardiovascular disease, namely, CTCF, JUN, JUND, NFATC1, NFE2L2, RAD21, RELA, and TAL1." (PMID 36105099, 2022).
metabolic disease (1 paper, 2021). A congenital disorder (due to inherited enzyme abnormality) or acquired (due to failure of a metabolically important organ) disorder resulting from an abnormal metabolic process. "Recently, JunD has emerged as a vital player in the setting of metabolic diseases." (PMID 34335468, 2021).
JUND also shares sentences with these, for which no sentence is quoted: fibrosarcoma (3 papers); lymphoma (3); oral cancer (3); neuroblastoma (2); acute leukemia (1); atherosclerosis (1); autism spectrum disorder (1); autoimmune disease (1); bladder cancer (1); brain tumors (1); cardiomyopathy (1); celiac disease (1); cholangiocarcinoma (1); clear cell sarcoma of the kidney (1); Cutaneous T-Cell Lymphomas (1); Diabetic Nephropathy (1); endometrial cancer (1); fibrosis (1); glioblastoma (1); hematological diseases (1); hepatic (1); Hyperinsulinemia (1); Intellectual disability (1); invasive breast carcinoma (1); ischemic stroke (1); lymphopenia (1); metastatic tumors (1); multiple myeloma (1); osteoporosis (1); periodontitis (1).
A further 8 diseases each share a sentence with JUND in 1 paper.